SOX2 (SRY-box transcription factor 2)
Diseases named in the same sentence as SOX2 in open-access papers (continued):
Sharing a sentence is not in itself a finding about the gene and the disease.
tumor (continued). "On immunohistochemistry, SOX2 was positive in a higher proportion of tumours WDLD compared with those meeting WHO lineage criteria, 7/10 v 10/42 (70 v 23.4%, p = 0.005)." (PMID 38483762, 2024). "In the present study, we have observed significant upregulation of OCT4 and SOX2 expression in tumor organoids treated with radiation indicating the stemness features associated with therapeutic resistance." (PMID 38429272, 2024). "It has been reported that SOX2 plays a role in proliferation, tumor growth, drug resistance, and metastasis in a variety of cancer types." (PMID 38275880, 2024). "The data demonstrated that there was about a 50% decrease in SOX2 expression in tumor organoids that were treated with 5 μM of 5-FU." (PMID 38429272, 2024). "SOX2 is involved in regulation of cisplatin response in tumor cells by regulation of Wnt-β-catenin pathway." (PMID 38956588, 2024). "These distinct preventive combinations and second-line treatment option dependent on NOTCH1 and SOX2 expression in TNBC are able to induce tumor growth control and reduce metastatic burden." (PMID 39478150, 2024). "The heterogeneous and poorly differentiated expression of OCT4 and SOX2 was found in tumor tissues, as compared to homogenous and well differentiated expression in normal pancreas." (PMID 38429272, 2024). "Quantitative image analysis of tumor sections revealed expression of N1-ICD and SOX2 in different areas within the same tumor." (PMID 39478150, 2024). "In particular, Oct4, Sox2, and Nanog are overexpressed in malignancies, and affect tumor transformation and metastasis." (PMID 39272290, 2024). "On the other hand, tumor neovascularization increases Sox2 expression, which in turn helps to maintain the CSC phenotype." (PMID 39098905, 2024). "Tumor cells with reduced SOX2 levels show increased expression of mesenchymal markers, which is accompanied by the loss of morphological characteristics of epithelial cells and an increase in SOX9 expression." (PMID 38275880, 2024). "SOX2 up regulation is observed in various cancers that increases tumor aggressiveness and poor prognosis." (PMID 38956588, 2024). "We have shown that WDLD tumours exhibit a higher expression of the stem cell marker SOX2, suggesting a possible involvement of stem cells in their development." (PMID 38483762, 2024). "All these data confirm the importance of SOX2’s presence in tumor strains to perform further investigations concerning the self-maintaining abilities of tumors and overcoming their therapeutic resistance." (PMID 38672069, 2024). "GSI treatment of HCC1599 xenografts likewise demonstrated transient and limited tumor growth control, while SOX2 expression rendered tumor cells insensitive to NOTCH inhibition, similar to iSOX2 MB157 xenografts." (PMID 39478150, 2024). "Conversely, when tumor organoids were treated with a combination of 5-FU and radiation, there was a significant inhibition in SOX2 and OCT4 expression, indicating CSC self-renewal inhibition." (PMID 38429272, 2024). "The results demonstrated combination of 100 μM of 5-FU and 4 Gy of radiation significantly suppressed OCT4 and SOX2 expression and inhibited tumor organoid growth as compared to untreated control (p < 0.05)." (PMID 38429272, 2024). "Stable LIN28B downregulation resulted in a significant decrease in the tumor markers SOX2, NESTIN, and SOX9 and an increase in the neural differentiation marker GAP43, consistent with the critical role of LIN28B in maintaining stemness." (PMID 38732012, 2024). "m6A mRNA modification is essential for cancer stem cell self-renewal and tumor metastasis, enhancing the frequency of tumor stem cell self-renewal, and cancer cell genesis and initiation by promoting the expression of SOX2 mRNA, a cancer stem cell marker." (PMID 38166703, 2024). "Specifically, SOX9 promotes tumor cells to non‐NE differentiation, such as bone or cartilage differentiation, while SOX2 promotes the determination of the NE lineage." (PMID 39372390, 2024).
tumor (continued). "Whereas tumor-specific Piezo2 knockout in SHH MBs disrupts the blood-tumor barrier, decreases the quiescence of Sox2+ MB cells, and enhances MB chemosensitivity." (PMID 38355808, 2024). "Knockdown of NUMB, or overexpression of NICD (the active fragment NOTCH1) or SOX2, rescued the in vitro sphere-forming and in vivo tumor-forming abilities that were lost upon RAB4A knockdown." (PMID 39463384, 2024). "LIFR silencing markedly impaired tumor formation and decreased CSCs frequency in vivo, accompanied by diminished SOX2, CD44 and ALDH1A1 expression in samples." (PMID 39206755, 2024). "SOX2 immunofluorescence was observed in tumours of different hormonal types (21/21) to varying degrees (0.05–38.24%), noting that transcription factors were not assessed." (PMID 38483762, 2024). "By comparison, the SOX2 positive tumours with distinct cell lineage demonstrated a lower range percentage of SOX2 positive (1–4%), with variable intensity of expression." (PMID 38483762, 2024). "SOX2 silencing significantly increased the number of tumor spheres with a significant reduction in colony size when compared to SOX9 silencing and control cell lines, whereas SOX9 silencing did not affect the tumor sphere formation or size of the colonies." (PMID 38275880, 2024). "Tumor areas enriched in cleaved caspase 3+ cells and cells expressing p21correlate with the accumulation of cells expressing Oct4, Sox2 and c-Myc." (PMID 39587064, 2024). "SOX2 expression is significantly higher in squamous cell carcinoma (SCC) CD34+ tumor initiating cells compared to CD34− cells." (PMID 38612911, 2024). "In gastric cancer, SOX2 expression was correlated with tumor suppressor activity by modulating the WNT/β catenin pathway in a mouse model." (PMID 38275880, 2024). "Overall, our results indicated that the bidirectional regulation between Notum and PI3K/AKT signaling pathway resulted in upregulation of Sox2, therefore enhancing GC stem cell-like traits and triggering tumor progression in GC patients." (PMID 37749430, 2024). "SOX2 expression was significantly correlated with increased clinical stage or greater tumor size, distant metastasis, and decreased overall and disease-free survival in AdCC." (PMID 39858584, 2024). "To illustrate these phenomena at the molecular level, we have shown that mesothelial cells co-cultured with tumor cells significantly enhanced the well-known and well-defined stemness markers Nanog, Oct3/4, Sox2, and ALDH1L1 in OvCa cells." (PMID 38575576, 2024). "In vitro findings reveal that silencing SOX2 enhances tumor radioresistance, while SOX9 silencing enhances radiosensitivity." (PMID 38275880, 2024). "This single cell transcriptomic analysis allowed us to identify the presence of macrophages (CD163), T cells (CD3D), and pericytes (PDGFRB), as well as endothelial (VWF) and folliculostellate (SOX2) cells, within the tumor microenvironment." (PMID 39217365, 2024). "Here, we sought to validate, in a xenograft mouse model, the essential role of NUMB, NOTCH1, and SOX2 in RAB4A-driven tumor formation." (PMID 39463384, 2024). "Various reports suggest that the transcription factor Sox2, a master regulator of embryonic and induced pluripotent stem cells, drives cancer stemness, fuels tumor initiation, and contributes to tumor aggressiveness via major drug resistance mechanisms." (PMID 38473392, 2024). "Sox2 expression defines both tumor-initiating and tumor-propagating MB cells capable of self-renewal and resistance to SMO inhibitors." (PMID 38689348, 2024). "Diffuse SOX2 expression was significantly correlated with high histological grade, mitoses, greater tumor size, recurrence, distant metastasis, and worst overall survival among patients with extracapsular CXPA." (PMID 39858584, 2024).
tumor (continued). "Consistent with the in vitro analysis, the protein levels of Nestin and SOX2 were decreased in tumor tissues." (PMID 39501082, 2024). "The co-regulation of LINC00857, LINC00968, LINC00663, and ITGA9-AS1 on SOX2 suggested their potential contributions in aberrant sialylation process during tumor progression." (PMID 38632255, 2024). "Consistently, tumours treated with alisertib, either alone or in combination, displayed over 70% reduction in SOX2 expression compared to the control group." (PMID 38467828, 2024). "Intriguingly, following NK cell killing, the CD133 level of surviving tumor cells was dramatically increased from 20% to 80%, accompanied by upregulation of SOX2, OCT4, and NANOG stem cell marker expression." (PMID 38494433, 2024). "Our findings suggest that SOX2 is highly expressed in various tumor tissues and has potential clinical significance." (PMID 38164286, 2024). "The identified epigenetic PARPi hallmarks contained hundreds of DMRs; however, only a few DMRs were reported as tumor driver genes (SOX2, POU2AF1, PTK6, VHL, JAK3, and EZH2) or as HRD genes (RAD51C)." (PMID 38927686, 2024). "Tumor cells in the MAF of this particular patient showed a molecular profile associated with chemoresistance, i.e. with high expression levels of SOX2 and ALDH1 measured by immunocytochemistry." (PMID 38974022, 2024). "Primary PDAC had significantly higher SOX2 epithelial expression compared to non-tumor tissue (P = 0.042)." (PMID 38532463, 2024). "In concert with these results, we report that MUC1 associates with ∆Np63, SOX2, and NOTCH3 expression in HNSCC tumor cells as determined by single-cell RNA sequencing (scRNA-seq) analysis." (PMID 38619287, 2024). "For the pan-cancer MSI analysis of SOX2, we calculated the Pearson's correlation coefficient for each tumor type." (PMID 38164286, 2024). "SOX2 epithelial/stromal expressions were positively correlated with the large tumor size in the primary AAC group (P = 0.052, P = 0.044, respectively)." (PMID 38532463, 2024). "After treatment, we performed immunofluorescence staining of OCT4 and SOX2 in tumor organoids to study their expression." (PMID 38429272, 2024). "Remarkably, the rare holoclone cells (∼ 10%) were characterized by high SOX2 expression (67-fold higher than paraclone cells) and higher capacity of xenograft tumor formation (269-fold higher than paraclone cells)." (PMID 39482615, 2024). "SOX2 is a transcription factor that maintains the regenerative capacity and pluripotencyof undifferentiated NSCs and specific tumor cell subgroups, including GBM stem cells." (PMID 38716541, 2024). "DEX was reported to reduces tumor incidence through reduction of inflammatory signaling required for SOX-2-driven tumorigenesis." (PMID 38864530, 2024). "Taken together, our study identified a novel mechanism of reciprocal inhibition between Notch signaling and SOX2 that shapes tumor cell plasticity and therapeutic escape in NOTCH-driven TNBC." (PMID 39478150, 2024). "In this study, we performed a pan-cancer analysis of SOX2 and analyzed the expression levels of SOX2 in different tumor subtypes and immune cells using the TCGA, GETX, and TSIDB databases." (PMID 38164286, 2024). "Our gene expression analysis indicates a reduction in the transcription of CD99 and CDKN1A and increased levels of SOX2 in ES tumors, the latter being consistent with the role of stemness in tumor progression." (PMID 38785514, 2024). "Of SOX2 positive WDLD tumours the percentage of SOX2 positive cells ranged from 1 to 46% with 6/7 exhibiting strongly positive staining intensity." (PMID 38483762, 2024).
tumor (continued). "We demonstrate that these tumours exhibit a higher expression of the stem cell marker SOX2 compared with other lineage-differentiated tumours, suggesting possible involvement of stem cells in their development." (PMID 38483762, 2024). "For stemness, miR-486-5p can modulate transcription factors such as OCT-4 and SOX-2, reducing self-renewal and tumor-initiating capabilities." (PMID 39766136, 2024). "Recent studies have reported that SOX2 induces resistance to radiotherapy in BC, which plays a pivotal role in the emergence of chemotherapy resistance in tumor cells." (PMID 38494478, 2024). "Similar to the observation made in the in vitro sphere formation assay, the expression of SOX2 partially but significantly restored the tumor forming ability, with about a 50-day delay in tumor growth." (PMID 39463384, 2024). "The sole expression of SOX2 is required for maintaining the tumor-initiating properties, being more than a marker but a critical factor for CSC functions." (PMID 37686421, 2023). "In vivo, the genetic ablation of CTH in the host led to a significant reduction of the tumor volume and the protumorigenic and stemness transcription factor sex determining region Y-box 2 (SOX2)." (PMID 37300955, 2023). "The increase in tumor incidence correlated with the maintenance of high expression of pluripotency genes Oct4, Sox2 and Nanog, elevated activity of the Nodal signaling pathway, and suppression of germ cell mitotic arrest." (PMID 37180974, 2023). "Notch, Wnt/β-catenin, and sonic hedgehog signaling pathways are known to play a decisive role in tumor stemness via regulating SOX2 and NANOG expression." (PMID 36396820, 2023). "The IF staining for Sox2 and Nestin of the tumor specimens demonstrated that in tumors treated with plant Vern extract or phytol, the expression levels of these CSC markers was highly reduced, by about 70%." (PMID 36900417, 2023). "These clinical and molecular characteristics arise from the participation of SOX2 in the formation and maintenance of tumor-initiating cells that resemble tissue progenitor cells, as evidenced by BRCA, GBM, LUAD and LUSC studies." (PMID 37738673, 2023). "Studies in Sonic Hedgehog (SHH) medolloblastomas unraveled that depletion of AHR drives tumor growth due to elevated activation of the TGFβ signaling and the enrichment of SOX2 positive cancer stem-like cells." (PMID 37151890, 2023). "Studies have shown that SOX2 promotes tumor cell stemness and plays a crucial role in triggering resistance to cancer therapies." (PMID 38012281, 2023). "The level of SOX2 expression in CRC is believed to confer to tumor metastasis and lymph node infiltration." (PMID 36827121, 2023). "SOX2 is an important regulator of cell fate during tumor development and cell reprogramming, which is closely related to stem cell renewal and drug resistance." (PMID 37744275, 2023). "Tumor cell pro-survival typically results in the upregulation of stem cell transcription factors, such as SOX2, Oct3/4, c-Myc and Nanog." (PMID 37809806, 2023). "Dysregulation in the expression genes of the pluripotency gene networks including OCT4, SOX2, NANOG and REX1 have been implicated in tumor development, and have been observed to result in poorer patient outcomes." (PMID 36980876, 2023). "The relation of Sox2 expression (and SOX2 gene copy number gain) with clinical outcomes is still a matter of debate, suggesting distinct roles for SOX2 depending on the tumor localization and histology." (PMID 37888115, 2023). "We confirmed that tumor stemness markers including SOX2, OCT4 and NANOG can be significantly upregulated by treatment of CM from H-TDE-stimulated MRC5 cells." (PMID 37781522, 2023).
tumor (continued). "Animal models have shown that TAMs activation in cancer cells leads to STAT3‐mediated Sox2 expression, resulting in an increase in the number of tumor stem cells and metastasis in a mouse breast cancer model." (PMID 38077251, 2023). "NKX2-1 and CK7 signals were downregulated, while altered expression of the p63 isoform and upregulated SOX2 were detected in KPU tumor lysates." (PMID 38093367, 2023). "Specifically, this is the first time that we found that SE‐lncRNA SUCLG2‐AS1 is linked to the tumour metastasis driver gene CTCF, contributing to SOX2 through the loop regulation ability to form RNA/DNA/DNA triplexes in NPC." (PMID 37658588, 2023). "We observed that, in all pHGG models, tumor cells remained similarly Nestin-positive and SOX2-positive in all investigated brain areas, including the pons, cerebellum and SVZ." (PMID 37328883, 2023). "We consistently found that overexpression of SOX2 resulted in significant increases in tumor volume and weight, which was effectively abrogated by treatment with the glycolysis inhibitor, 2-DG." (PMID 38044399, 2023). "Further, in in vivo xenograft models, inhibition of Sox2 restrained tumor growth and repressed chemoresistance." (PMID 36768876, 2023). "A study has indicated that in OSCC, the LIN28B-Let7 axis enhances tumor cell stemness and promotes tumorigenesis by mediating SOX2 expression through HMGA2." (PMID 37237385, 2023). "The expression of SOX2 was significantly higher in tumor tissues than in adjacent normal tissues of NSCLC samples in TCGA." (PMID 37213675, 2023). "Taken together, our findings show WAC-AS1 is a tumor promoter and a key regulator of OS cell stemness and metastasis via a miR-5047/SOX2 axis." (PMID 37957698, 2023). "Taken together, our data suggest that Sox2 can act as a tumor suppressor for adenocarcinoma formation in this model at least partly by preventing emergence of dual-positive cells." (PMID 37882674, 2023). "Intriguingly, systematic analysis of mutated tumor genes identified EGFR, MET, BRAF, and TERT as determinants in LUAD, and NOTCH, FGFR1, SOX2, and PI3CA as determinants in LUSC." (PMID 37046851, 2023). "Enhanced expression of Oct4, Sox2, and/or Nanog are characteristic for primary OvCa tumors, and their expression enhances chemoresistance and potential of tumor relapse." (PMID 37958844, 2023). "CAGE was necessary for tumor spheroid forming potential and the increased expression of SOX-2 PC-9 cells." (PMID 37735252, 2023). "Decreased expression of BCSC stemness regulators ALDH1A1 and SOX2 were observed in the tumor spheres treated with Z8." (PMID 37147285, 2023). "There were positive correlations among USP13, MYC, and SOX2 at the protein level in human LUSC Clinical Proteomic Tumor Analysis Consortium (CPTAC) proteomic data." (PMID 38093367, 2023). "It has been shown that the stem cell transcription factor SOX2 + interferes with the tumor suppressive Hippo pathway, leading to high YAP function and the repression of the differentiated state in the cancer stem cells in osteosarcomas." (PMID 37109772, 2023). "It was demonstrated that higher expression of Sox2 was detected by immunostaining in metastasis specimens compared to primary tumor." (PMID 37958844, 2023). "We observed a slight significant difference for SOX2 between primary parental tumor and PDOs in four tumors (tumor #1, tumor #10, tumor #22, and tumor #23." (PMID 38037472, 2023). "We also examined the relationship between SOX2 copy number and SOX2 overexpression within these six tumor types." (PMID 37738673, 2023). "Most studies on SOX2 have concluded that protein overexpression is significantly correlated with tumor recurrence and poor prognosis, which is compatible with its function as a transcription factor linked to stemness." (PMID 37888115, 2023). "NANOG also works together with other stemness factors, such as KLF4, MYC, OCT4, or SOX2, to control target genes that have important functions in embryonic stem cells and, plausibly, in tumor cells." (PMID 37165076, 2023).